EGFR (epidermal growth factor receptor)
Diseases named in the same sentence as EGFR in open-access papers (continued):
Sharing a sentence is not in itself a finding about the gene and the disease.
glioblastoma (continued). "Furthermore, dacomitinib has shown promising results in early-phase clinical trials for patients with recurrent glioblastoma who have EGFR amplification, with or without EGFRvIII." (PMID 38264122, 2023). "Here, we performed an integrated analysis of 50 glioblastomas IDH wildtype with or without EGFR gene amplification, and performed epigenome-wide methylation analysis to reveal distinct differences in the glioblastoma methylome and subsequently affected pathways." (PMID 37444635, 2023). "They lacked EGFR amplification, lacked combined trisomy of chromosome 7 plus monosomy of chromosome 10, and only rarely had TERT promoter mutation or CDKN2A homozygous deletion, which are hallmarks of conventional IDH-wildtype glioblastoma." (PMID 38079020, 2023). "Well-known somatic drivers of glioblastoma (GBM) heterogeneity, including PDGFRA, IDH1, EGFR, and NF1, have altered how we treat patients, diagnose disease, and design clinical trials." (PMID 37252795, 2023). "In glioblastoma (GBM), DYRK1A was found to be highly expressed in EGFR-amplified tumors, whereas doxycyclin-inducible shRNA depletion of DYRK1A decreased tumor growth in the orthotopic xenograft models." (PMID 37900285, 2023). "Drug resistance may be able to explain why the response to EGFR targeted therapies is not efficient for glioblastoma." (PMID 37446288, 2023). "Finally, we also describe the significance of lipid droplets in glioblastoma and the impact of fatty acid synthesis, particularly docosahexaenoic acid (DHA), on cell membrane fluidity and signal transduction from the epidermal growth factor receptor (EGFR)." (PMID 37046844, 2023). "Their histology shows similarities to secondary glioblastomas that occur at an earlier age, considering readily observed absence of EGFR positivity, which may also account for the younger age observed in CPA glioblastomas." (PMID 36932101, 2023). "produced OV-IL15C, a herpes simplex 1-based human IL15/IL15Rα sushi domain fusion protein, as well as commercial EGFR-CAR NK cells, and examined their efficiency as a monotherapy and in combination in vitro and several glioblastoma (GBM) mice models." (PMID 36703982, 2022). "Likewise, though gefitinib, erlotinib, and afatinib inhibited EGFR in vitro, reduced proliferation and angiogenesis in glioblastoma cells, these results were not confirmed in the clinic." (PMID 35214064, 2022). "Finally, the in vivo anti-tumor efficacy study in intracranial xenograft models demonstrated that EGFR mAb-EV-Ver-A effectively inhibited glioblastoma growth, but the combination with VEGF mAb did not improve the therapeutic efficacy." (PMID 35052809, 2022). "Indeed, Gint4.T, an RNA aptamer that can bind and downregulate PDGFRβ, promotes a decrease in proliferation and migration in glioblastoma multiforme cells, while CL4, an RNA aptamer against EGFR, demonstrated an encouraging effect against EGFR-positive tumoral cells." (PMID 35806476, 2022). "In this study, we explored alterations in 3D chromatin organization of EGFR-amplified glioblastoma and its subsequent impact by performing a comparative analysis of Hi-C, RNA-seq, and whole-genome sequencing (WGS) on EGFR-amplified glioblastoma-derived A172 and normal astrocytes (HA1800 cell line)." (PMID 35521558, 2022). "Interestingly, a broad range of actionable fusion genes were identified in this cohort of glioblastomas including EGFR-SEPT, EFGR intragenic recombination, FGFR3-TACC3, PTPRZ1-MET, CAPZA2-MET, METex14 skipping, AGK-BRAF, EGFR Viii, TBLXR1-PIK3CA and FIP1L1-PDGFRA." (PMID 35324914, 2022). "In the GBM-LIPO trial, we treated patients with relapsed glioblastoma harboring an EGFR amplification with anti-EGFR ILs-dox and assessed its pharmacokinetics within the CNS compartment." (PMID 34998092, 2022).
glioblastoma (continued). "However, while many inhibitors and antibodies for epidermal growth factor receptor have demonstrated promising anti-tumour effects in preclinical models, they have failed to improve outcomes for glioblastoma patients in clinical trials." (PMID 36497413, 2022). "Given that RRAD induces EGFR and STAT3 activation and RRAD knockdown sensitizes chemoresistant cancer cells to cytotoxic drugs, targeting STAT3 with oxelaidin or butamirate may attenuate temozolomide resistance and glioblastoma recurrence after treatment." (PMID 33980886, 2021). "In the present study, canine osteosarcoma, human osteosarcoma and glioblastoma cell lines, exhibited similar response to single CT treatment and cancer cell death was further enhanced by introducing another STAT3/5 inhibitor, a proteasome inhibitor drug, and an EGFR/ErbB2 inhibitor." (PMID 33544704, 2021). "For instance, NEAT1, a glioblastoma-associated lncRNA, was an oncogenic factor that was regulated by EGFR pathway, by activating WNT/β-Catenin pathway to promote GBM cells growth and invasion." (PMID 34772911, 2021). "Moreover, EGFR is the top gene with the highest amplification frequency in the TCGA database of Glioblastoma Multiforme (PanCancer Atlas) (data not shown)." (PMID 34461927, 2021). "We found that EGFR and ERBB2 mRNA expression levels were higher in glioblastoma (GBM, WHO IV) than in other grades (WHO grade II & III), while the ERBB3 and ERBB4 mRNA expression levels were the opposite." (PMID 33892666, 2021). "Likewise, the results of clinical trials exploring EGFR and mTOR inhibition in unselected glioblastoma patients with a one-size-fits-all approach were negative." (PMID 32756332, 2020). "The human epithelial GFR family, including EGFR, Her2, Her3 and Her4, has been found to play an essential role in tumor growth, migration, survival, metastasis, adhesion and angiogenesis not only in HNSCC but also in glioblastoma, lung, breast, gastric and colorectal cancers." (PMID 33202816, 2020). "However, a phase II trial of EGFR-TKI plus mTOR inhibitor in adults with recurrent glioblastoma failed to gain satisfactory results." (PMID 32041519, 2020). "In this study, the crosstalk activation of epidermal growth factor receptor (EGFR) and mesenchymal-epithelial transition factor (MET) signaling pathways is demonstrated to contribute to temozolomide (TMZ) resistance, resulting in an unfavorable prognosis for patients with glioblastoma." (PMID 32001707, 2020). "An open-label phase II single-center study of 53 patients with recurrent glioblastoma (not selected by EGFR status) found no objective tumor response with gefitinib at 500 mg daily (with protocol to escalate to 750 mg then 1000 mg as tolerated), though it was well-tolerated." (PMID 33187135, 2020). "We aimed to elucidate new role of mTOR in EGFR-mutant (EGFR-mut) non-small cell lung cancer (NSCLC) and glioblastoma (GBM) with a focus on tumor microenvironments." (PMID 32923403, 2020). "Besides glioblastoma, amplified PDGFRA and EGFR may also occur in lower-grade gliomas and in their recurrent tumors." (PMID 33081688, 2020). "Overexpression of EGFRvIII, a truncation mutant of EGFR which is activated in absence of ligand, in glioblastoma cells has been shown to radically alter the regulation of sEV biogenesis and sEV contents, favouring the secretion of pro-invasive proteins such as CD44." (PMID 33302515, 2020). "The resilience of EGFR amplification and EGFRvIII in glioblastoma may represent a failure of our drugs to act against the specific EGFR alterations in glioblastoma, rather than an indictment of the validity of targeting the EGFR axis in glioblastoma." (PMID 33187135, 2020). "Dacomitinib was evaluated in a multicenter open-label phase II in 30 patients with recurrent glioblastoma (split across cohort A with EGFR gene amplification without EGFRvIII, and cohort B with both EGFR gene amplification and EGFRvIII), with the drug dosed at 45 mg daily." (PMID 33187135, 2020).
glioblastoma (continued). "This is also the case in epidermal growth factor receptor (EGFR), which is overexpressed in human tissues and cell cultures of glioblastoma multiforme (GBM)." (PMID 32605009, 2020). "A lack of EGFR amplification in GS is a molecular marker that makes it distinct from glioblastoma." (PMID 31218139, 2019). "Furthermore, combining the HDAC inhibitor vorinostat with a multitargeted tyrosine kinase inhibitor (TKI), vandetanib, can prevent EGFR, vascular EGFR (VEGFR), and Ret-dependent signaling, thereby inhibiting growth, preventing Akt signaling, and stimulating apoptosis in glioblastoma cells." (PMID 31013819, 2019). "Correspondingly, tumor reduction by Nutlin-3a treatment could no longer be detected in U87 glioblastoma grafts expressing EGFR." (PMID 30910997, 2019). "To address these limitations, we envisioned the development of a robust EGFR aptamer by rationale truncation and chemical modifications of the existing 39mer CL4 and extend its potential by evaluating in various cancer cells including malignant glioblastoma cells." (PMID 31546749, 2019). "Thus, HDAC inhibitor combined with erlotinib is a promising treatment option for newly diagnosed, treatment-naïve tumors irrespective of their EGFR status, and for treatment-refractory EGFR-overexpressing glioblastoma." (PMID 31013819, 2019). "Hence, we analyzed transcriptome data from glioblastoma cell line SF767 to predict target genes regulated by EGFR isoforms II-IV, but not by EGFR isoform I nor other receptors such as HER2, HER3, or HER4." (PMID 31438847, 2019). "Among the identified molecular mechanisms, in glioblastoma multiforme (GBM), IPA induces c-Cbl-mediated EGFR ubiquitination, inhibiting its downstream signaling." (PMID 31569395, 2019). "Moreover, the combination of sirolimus, an inhibitor of mTOR, and EGFR-TKIs did not improve the responsiveness in patients with recurrent glioblastomas." (PMID 31284441, 2019). "Glioblastoma multiforme (GBM) is a highly aggressive brain tumor with a dismal prognosis, and the patients carrying EGFR-driven tumors with PTEN mutation do not respond to anti-EGFR therapy." (PMID 30595797, 2018). "We have found that SEMA3C stimulates EGFR and MET signaling in a broad range of cancer cell lines including bladder, and renal cancer as well as glioblastoma, suggesting that SEMA3C may be an important growth factor for a broad spectrum of cancers in addition to PCa." (PMID 29348142, 2018). "Furthermore, EGFR-amplified glioblastoma cells lacked co-expression with the EMT molecules SLUG or TWIST." (PMID 29844871, 2018). "CL4 displays a therapeutic effect against EGFR activation; however, EGFR inhibitors have failed to prove success as monotherapies for glioblastoma, as such, CL4 should be used as a shuttle for therapeutic or diagnostic agents to these tumours in order to have clinical success." (PMID 29189740, 2017). "BsAb that target EGFR and HER2 may be an effective strategy for the treatment of glioblastoma." (PMID 28931402, 2017). "Moreover, a statistically significant correlation between (IDH, EGFR) genetic alterations and age of patients was not acquired to help a better distinction of both forms of glioblastomas." (PMID 28785587, 2017). "Therefore, targeting ERBB receptor family members like EGFR, ERBB2 or ERBB3 alone or in combination with other epithelial markers such as EpCAM, will provide opportunities to detect and isolate CTCs that represent primary tumors of ovarian and glioblastoma." (PMID 29321816, 2017). "HDAC9 is overexpressed in GBM patients with poor prognosis and promotes tumor formation of glioblastoma via activation of the TAZ-mediated EGFR pathway." (PMID 28513547, 2017). "Moreover, we showed that PTUPB may exert anti-glioblastoma effects by suppressing expression of hyaluronan mediated motility receptor (HMMR) and by targeting epidermal growth factor receptor (EGFR) signaling pathway." (PMID 29152086, 2017).
glioblastoma (continued). "In glioblastomas (GBM), the most common alterations were gene amplifications (PDGFRA, KIT, KDR, EGFR, and MET) and deletions (CDKN2A and PTEN)." (PMID 27172220, 2016). "A mutant form of epidermal growth factor receptor (EGFR), EGFRvIII, is common in glioblastoma (GBM) and confers enhanced tumorigenic activity and drug resistance." (PMID 26778701, 2016). "The lack of EGFR amplification in IDHmut glioblastoma was also seen in the TCGA samples." (PMID 26091668, 2015). "In glioma, genome-wide association studies have identified common genetic variations in 7 genes that increase glioma risk (TERT, EGFR, CCDC26, CDKN2A, CDKN2B, PHLDB1 and RTEL1) but BRCA1 is not among them and there is no known association between BRCA1 gene and glioblastoma multiforme (GBM)." (PMID 25880076, 2015). "There is a general agreement that EGF functioning is increased in GBM (glioblastoma multiform),but it is not yet clear whether this is due to over-activity of the receptor (EGFR), or to increasedlevels of the ligand." (PMID 23637756, 2013). "Finally, the TCGA dataset supports the prognostic value of the ZEB1/miR-200/c-MYB pathway for glioblastoma, as well as significant co-occurrence of ZEB1, MGMT and ROBO1 in these tumours, and decreased levels of EGFR phosphorylation with reduced ZEB1 expression." (PMID 23818228, 2013). "Recent data described heterozygous deletions of the NF-kB Inhibitor alpha gene (NFKBIA) in about 20% of glioblastomas (GBM): deletions were mutually exclusive with epidermal growth factor receptor (EGFR) amplification, a frequent event in GBM." (PMID 24330732, 2013). "However, the frequency of EGFR expression shown in the present data was inconsistent with another study stating that EGFR amplification was identified in 40–50% of glioblastomas and ∼10% of anaplastic astrocytomas, but not in low-grade astrocytomas." (PMID 23946790, 2013). "Glioblastomas exploit various molecular pathways to promote glutamate- dependent growth by activating the AMPA (2-amino-3-(3-hydroxy-5-methyl-isoxazol-4-yl) propanoic acid) receptor, the group II metabotropic glutamate receptor, mGluR, and the epidermal growth factor receptor, EGFR." (PMID 23724064, 2013). "Primary glioblastoma that develops without precursor lesions shows an amplification of the epidermal growth factor receptor (EGFR) gene more frequently than secondary glioblastoma that generates via the stepwise progression from the pre-existing low-grade glioma." (PMID 22494416, 2012). "Not surprisingly, over expression of EGFR in some glioblastoma samples is also observed here." (PMID 20423517, 2010). "Although our study was not designed to statistically evaluate the effect of osimertinib across the spectrum of EGFR altered glioblastoma, these data showed that osimertinib failed to robustly inhibit 18F-FDG uptake in this cohort of EGFR-altered GBM patients per the PERCIST criteria." (PMID 40051661, 2025). "For instance, in glioblastoma, circular E-cadherin RNA (circ-E-Cad) produces a secretory E-cadherin protein variant through multiple-round open reading frame (ORF) translation, activating EGFR signaling independent of EGF and maintaining glioma stem cell tumorigenicity." (PMID 38802795, 2024). "Depatuxizumab mafodotin (ABT-414), which consists of an EGFR-specific humanized antibody, a non-cleavable malemidocaproyl linker, and monomethyl auristatin F, was tested for patients with EGFR-amplified newly diagnosed glioblastoma but discontinued due to a lack of survival benefit." (PMID 38107063, 2023). "Recently, Osimertinib could not only inhibit EGFR-negative glioblastoma patient-derived xenograft (PDX), possibly via regulation of MAPK pathway, but also inhibit transcription factor EGFR-TAZ, providing a novel insight for drug reuse of EGFR-targeted inhibitors." (PMID 35135556, 2022). "However, the EGFR inhibitors failed to improve overall survival in glioblastoma patients." (PMID 36267281, 2022).
glioblastoma (continued). "This contrasts with non-midline cortical pHGG, which do not commonly carry EGFR alterations; and is similar to adult glioblastoma (GBM), with as many as 60% of GBMs carrying EGFR amplification." (PMID 35978801, 2022). "Moreover, the EGFR downstream pathways phosphatidylinositol-4,5-bisphosphate 3-kinase (PI3K)-AKT-mechanistic target of rapamycin kinase (mTOR) signaling and mitogen-activated protein kinase (MAPK) signaling are prominently deregulated and favor therapy resistance in glioblastoma." (PMID 34771501, 2021). "As ligand-independent oligomers would dominate in glioblastoma cells where EGFR concentrations are high, but not in normal cells that rely on classic ligand-dependent dimerization, the EGFR oligomer may be another source of specific epitopes not seen on normal cells." (PMID 33187135, 2020). "Furthermore, EGFR amplification was found to be rare or nonexistent in pediatric glioblastomas." (PMID 32290213, 2020). "However, the effects of osimertinib on glioblastoma have not been examined, and there are concerns that glioblastoma might be resistant to osimertinib, similar to other EGFR-TKIs." (PMID 31284441, 2019). "Amplification of epidermal growth factor receptor (EGFR) and active mutant EGFRvIII occurs frequently in glioblastoma (GBM) and contributes to chemo/radio‐resistance in various cancers, especially in GBM." (PMID 31508283, 2019). "In another study, EGFR transactivation, which may contribute to cell migration, induced by HSP90a in U87 glioblastoma cells was inhibited with the down-regulation of TLR4, indicating that HSP90a promotes glioblastoma cells migration through the interacting with TLR4." (PMID 29029545, 2017). "Thus, 7 mutated cases were probably secondary glioblastomas and 15 cases could be primary GBM with EGFR amplified and nonmutated IDH." (PMID 28785587, 2017). "EGFR activates ERK1/2-dependant nuclear translocation of PKM2 and activates Myc, which in turn up-regulate GLUT1, LDHA and PKM2 expression in human glioblastoma multiforme (GBM) cells." (PMID 26147004, 2015). "In addition, patients suffering from recurrent glioblastoma with EGFR amplification and those lacking EGFRvIII expression have been treated with the EGFR-targeted monoclonal antibody cetuximab with a significantly superior progression-free and overall survival." (PMID 24205362, 2013). "The authors showed further that a proportion of vascular cells within human GBM contained genetic alterations that are typically encountered in glioblastoma cells (such as EGFR amplification) and are typically not seen in vascular endothelial cells." (PMID 23143192, 2012). "Although such mechanisms have not yet been described in GBM, the intrinsic plasticity of glioblastoma stem cells and the frequent activation of bypass pathways (e.g., EGFR, MET, PDGFR) suggest that resistance could also emerge in this context." (PMID 41002392, 2025). "At the molecular level, GBM is characterized by the absence of isocitrate dehydrogenase (IDH) gene mutations (glioblastoma, IDH-wild type) and specific genetic alterations in the TERT promoter, chromosomes 7/10, and the EGFR gene." (PMID 40076445, 2025). "This thalamic glioblastoma WHO grade 4, MGMT methylated, EGFR non-amplified, shows clear differences compared to the previous case, on multiparametric MRI." (PMID 40227555, 2025). "The case of a 38-year-old female patient shows a frontal glioblastoma WHO grade 4, with involvement of the genu of the corpus callosum, MGMT unmethylated, EGFR non-amplified." (PMID 40227555, 2025).